THUMPD3 (THUMP domain 3 tRNA guanosine methyltransferase)
Description:
Catalytic subunit of the THUMPD3-TRM112 methyltransferase complex, that specifically mediates the S-adenosyl-L-methionine-dependent N(2)-methylation of guanosine nucleotide at position 6 (m2G6) in tRNAs. This is one of the major tRNA (guanine-N(2))-methyltransferases. Also catalyzes the S-adenosyl-L-methionine-dependent N(2)-methylation of guanosine nucleotide at position 7 of tRNA(Trp).
Synonyms: DKFZP434F091
Tractability: PROTAC: ubiquitination databases record sites on it; its protein half-life has been measured.
Gene: Protein-coding gene on chromosome 3 (9,362,967 to 9,386,791, forward strand). Ensembl gene ENSG00000134077.
Subcellular location: Cytoplasm
Subcellular location (Human Protein Atlas): Cytosol; Nucleoli
Gene Ontology:
Molecular function: protein binding; tRNA (guanine(6)-N2)-methyltransferase activity; tRNA (guanine(7)-N2)-methyltransferase activity; tRNA (guanine) methyltransferase activity; RNA binding; RNA methyltransferase activity
Biological process: tRNA methylation
Cellular component: cytoplasm; cytosol; nucleolus; tRNA methyltransferase complex
Genetic constraint (gnomAD): Loss-of-function variants: 35 observed, 46.28 expected, observed/expected ratio (o/e) 0.76, 90% interval 0.58 to 1. The upper end of that interval is the gene's LOEUF score, 1, which puts it in group 4 of 6, group 1 being the genes least tolerant of losing a copy. Missense variants: 540 observed, 560.96 expected, observed/expected ratio (o/e) 0.96, 90% interval 0.9 to 1.03. Synonymous variants: 183 observed, 193.52 expected, observed/expected ratio (o/e) 0.95, 90% interval 0.84 to 1.07.
Homologues: Orthologues: chimpanzee THUMPD3 (99% identical), macaque THUMPD3 (97% identical), dog THUMPD3 (86% identical), pig THUMPD3 (85% identical), rabbit THUMPD3 (84% identical), guinea pig THUMPD3 (83% identical), mouse Thumpd3 (80% identical), rat Thumpd3 (80% identical), tropical clawed frog thumpd3 (59% identical), zebrafish thumpd3 (54% identical), Caenorhabditis elegans M04B2.2 (31% identical). Paralogues in human: THUMPD2 (22% identical).
Diseases named in the same sentence as THUMPD3 in open-access papers:
THUMPD3 is named in the same sentence as 7 diseases in open-access papers, as found by Europe PMC text mining. Sharing a sentence is not in itself a finding about the gene and the disease. The quoted sentences say what the papers report.
colon cancer (2 papers, 2022 to 2024). "Our findings indicated that DEDD2, GTF2H5, SNRPA1, BICD1, CELF1, and CLK3 were prognostic risk factors for colon cancer, while ADAD1, CMTR1, HNRNPUL1, FTSJ3, WDR43, THUMPD3, SNRPF were prognostic protective factors." (PMID 36212157, 2022).
Intellectual disability (2 papers, 2021 to 2024). "Previous research has indicated that the THUMPD3 gene is located in the 3p25.3 region, and interstitial deletions in this region lead to the 3p-syndrome, causing intellectual disability in patients." (PMID 39656728, 2024).
glioma (1 paper, 2023). A benign or malignant brain and spinal cord tumor that arises from glial cells (astrocytes, oligodendrocytes, ependymal cells). "By analyzing the CGGA dataset, the expression of THUMPD3 in the GBM group was not significantly changed compared with that in the LGG group, while the expression of TRMT112 in the GBM group was significantly increased compared with that in the grade II glioma group." (PMID 37864150, 2023).
Hypertension (1 paper, 2013). The presence of chronic increased pressure in the systemic arterial system. "Among the down-regulated DEGs in the MCA of the hypertension only group were FOXN1, NSRP1 and THUMPD3." (PMID 23874591, 2013).
lung adenocarcinoma (1 paper, 2024). A carcinoma that arises from the lung and is characterized by the presence of malignant glandular epithelial cells. "We next investigated whether depletion of THUMPD3 impacts the metastatic potential of lung adenocarcinoma cells, a crucial hallmark of cancer." (PMID 39656728, 2024). "Of these, we also identified that THUMPD3 is more highly expressed (more than 2-fold) in lung adenocarcinoma (A549 and H1975) cells than in normal IMR-90 lung fibroblasts." (PMID 39656728, 2024). "In initial analyses, siRNA and shRNA approaches were employed to deplete THUMPD3 from human lung adenocarcinoma cells (A549)." (PMID 39656728, 2024).
cancer (3 papers, 2021 to 2024). A tumor composed of atypical neoplastic, often pleomorphic cells that invade other tissues. "The functional significance of TRMT11/THUMPD2/THUMPD3-mediated tRNA m2G modifications in cancer cells remains largely unexplored compared to extensively investigated modifications such as m7G and m5C." (PMID 39019857, 2024). "Therefore, further validation is required to ascertain the involvement of TRMT112 and TRMT11/THUMPD2/THUMPD3 in the proliferation of diverse cancer cells." (PMID 39019857, 2024). "Our research reveals that some of the DEirlncRNAs included in the modeling play vital roles in the malignant phenotype of many cancers, such as MYLK−AS1, THUMPD3 − AS1, and DSCR8, especially in the development of HCC." (PMID 34923955, 2021). "However, the concomitant absence of both THUMPD3 and TRMT11 results in an almost complete loss of m2G in tRNAs and strongly affects the proliferation of the HCT116 cancer cell line." (PMID 37283053, 2023).
tumor (2 papers, 2022 to 2024). "We further demonstrate that THUMPD3 maintains expression of an extra-domain B (EDB) containing pro-tumour isoform of Fibronectin-1 mRNA, encoding FN1, an important ECM protein." (PMID 39656728, 2024). "NUTM2A − AS1, NUTM2B − AS1, SNHG3, and THUMPD3 − AS1 were found to be highly expressed in tumor samples." (PMID 35615532, 2022). "Finally, NUTM2A − AS1, NUTM2B − AS1, SNHG3, and THUMPD3 − AS1 were identified to be highly expressed in tumor samples and were negatively correlated with prognosis." (PMID 35615532, 2022).